LMX1B (LIM homeobox transcription factor 1 beta)
Diseases named in the same sentence as LMX1B in open-access papers (continued):
Sharing a sentence is not in itself a finding about the gene and the disease.
glaucoma (continued). "Cross-referencing with human genome-wide association studies data revealed overlap with glaucoma-associated genes (LTBP2, LOXL1, COL11A1, VCAM1), alongside reduced expression of Angpt and Lmx1b, linked to ocular hypertension." (PMID 41443436, 2025). "We have previously demonstrated that mice with a dominant mutation in Lmx1b (Lmx1bV265D/+) develop IOP elevation and glaucoma." (PMID 40272416, 2025). "To understand the role of LMX1B in TM function and glaucoma, we single-cell sequenced limbal cells from Lmx1bV265D/+ mutant mice (2,491 TM cells)." (PMID 39829808, 2025). "Homeobox genes such as SIX6/SIX1, LMX1b and MEIS, which play prominent roles in development, have been shown to be associated with glaucoma." (PMID 36148008, 2022). "Still, further research is necessary to better understand the role of LMX1B in glaucoma pathogenesis." (PMID 34440309, 2021). "For instance, PAX6 and LMX1B are both associated with ASD which, in turn, is associated with an increased risk of glaucoma." (PMID 34440692, 2021). "Future work is required to characterize specific modifiers, to understand the disease risk of individuals with LMX1B mutations, and to provide molecular targets for therapies to treat IOP elevation and glaucoma." (PMID 33462143, 2021). "Variants in the LIM homeobox transcription factor 1-beta (LMX1B) gene predispose individuals to elevated intraocular pressure (IOP), a key risk factor for glaucoma." (PMID 33462143, 2021). "Association analysis of rs35934224 in TXNRD2 and rs6478746 in LMX1B with primary open-angle glaucoma." (PMID 34408771, 2021). "In conclusion, this study lays a strong foundation for better understanding the mechanisms by which LMX1B contributes to glaucoma and for characterizing new therapeutic targets." (PMID 33462143, 2021). "We compared the phenotypic characteristics and optic disc parameters of glaucoma patients between the GC and GG genotype in the SNP rs187699205 at chromosome 9:129449650 in the intron of LMX1B gene." (PMID 34440426, 2021). "A mouse model carrying a dominant-negative mutation of Lmx1b was demonstrated to develop high IOP, abnormalities of the iridocorneal angle, and abnormal TM, which are all critical risk factors for developing glaucoma in humans." (PMID 34408771, 2021). "Functional studies support intraocular pressure-related influences of FMNL2 and LMX1B, with certain Lmx1b mutations causing high IOP and glaucoma resembling POAG in mice." (PMID 29891935, 2018). "We also investigated 9 novel glaucoma-associated loci from UKB in GERA, and 6 of the novel loci replicated at Bonferroni significance (near IKZF2, CADM2, near DGKG, ANKH, EXOC2, and LMX1B)." (PMID 29891935, 2018). "LMX1B gene encodes LIM (Lin-1, Isl-1, and Mec-3)-homeodomain transcription factor 1 beta, and rare deleterious mutations in LMX1B cause NPS, with glaucoma being one of the manifestations of the syndrome." (PMID 29891935, 2018). "Mutations in the LIM homeobox transcription factor 1-beta (LMX1B) are a cause of nail patellar syndrome, a condition characterized by skeletal changes, glaucoma and focal segmental glomerulosclerosis." (PMID 28059119, 2017). "Notably, LMX1B, an important gene in glaucoma GWAS, is among the most strongly activating TFs in TM cells." (PMID 39829808, 2025). "Furthermore, variants in LMX1B have been associated with POAG, including the identification of protective haplotypes seen less frequently in patients with glaucoma or elevated IOP." (PMID 34440426, 2021). "Animal studies have also provided further evidence for the role of Lmx1b in glaucoma." (PMID 34408771, 2021). "Besides, specific Lmx1b mutations were also recently reported to cause increased IOP and glaucoma resembling POAG phenotype in mice with variable anterior segment developmental anomalies that were dependent on the genetic background." (PMID 34408771, 2021).
glaucoma (continued). "Interestingly, in our Primary Open-Angle African American Glaucoma Genetics (POAAGG) GWAS study, the variants in LMX1B were significantly associated with mean deviation (MD) baseline, but not with IOP." (PMID 34440426, 2021). "The genetic loci that modify glaucoma susceptibility in individuals with LMX1B variants are not known." (PMID 33462143, 2021). "The current study identifies a total of nine novel loci associated with the risk of POAG or glaucoma at genome-wide significance that replicated in an independent sample, and demonstrates relevant function of FMNL2 and LMX1B using cell line and mouse experiments." (PMID 29891935, 2018). "This demonstration that Lmx1b mutations result in elevated IOP and glaucomatous nerve damage in eyes without developmental defects, supports the notion that LMX1B affects the risk of glaucoma in the absence of obvious developmental anomalies in human eyes." (PMID 29891935, 2018). "Finally, functional characterization of FMNL2 and LMX1B points to a mechanistic effect on IOP levels, which supports their role as glaucoma risk genes." (PMID 29891935, 2018). "Thus, we hypothesized that the metabolic abnormalities in TM3 cells underlie the IOP elevation that causes glaucoma, and that NAM treatment may protect the Lmx1b mutant TM." (PMID 39829808, 2025). "The LMX1B gene is a genetic susceptibility factor for POAG, and several single-nucleotide polymorphisms (SNPs) were shown to be associated with POAG in our own prior Primary Open-Angle African American Glaucoma Genetics (POAAGG) study genome-wide association study (GWAS)." (PMID 34440426, 2021). "Previous reports show that Lmx1b heterozygous null alleles do not cause glaucoma in mice." (PMID 33462143, 2021). "By analyzing Lmx1bV265D/+ mutant mice (develop elevated IOP and glaucoma), we show that mitochondrial pathways are primarily disturbed in the TM3 cell subtype, which most strongly expresses Lmx1b." (PMID 39829808, 2025). "Second, utilizing mutant mouse strains, we demonstrate support for a role of LMX1B in the pathogenesis of ocular hypertension (OHTN) and glaucoma in the general population." (PMID 29891935, 2018). "Here, to functionally evaluate whether Lmx1b mutations can cause glaucoma without obvious developmental anomalies, we studied the effects of the same mutation on two different genetic backgrounds, and a new mutation that has not previously been functionally characterized." (PMID 29891935, 2018). "Recent GWAS indicate that LMX1B variants cause elevated IOP and glaucoma in the general human population, without evident anterior segment abnormalities, involvement of other organs/tissues or NPS diagnosis." (PMID 33462143, 2021). "Glaucoma is one of the manifestation of classical NPS, but we are not aware of the report of an association of autism with LMX1B mutation in NPS." (PMID 28059119, 2017). "LMX1B mutations are well established to cause open-angle glaucoma in NPS patients, but due to the influence of modifier genes may also cause glaucoma without NPS." (PMID 24809698, 2014). "Other genes, including FOXC1, CYP1B1, LMX1B and MYOC were not expressed substantially in any neural retina cell classes, consistent with their proposed role predominantly in the anterior segment with mutations leading to high intraocular pressure, a major risk factor for glaucoma." (PMID 32555229, 2020).
Nephropathy (17 papers, 2009 to 2025). A nonspecific term referring to disease or damage of the kidneys. "The manifestations of LMX1B-associated nephropathy and Alport syndrome can overlap because they share abnormalities in type IV collagen." (PMID 41299396, 2025). "The manifestations of LMX1B-associated nephropathy and Alport syndrome can overlap because they share abnormalities in type IV collagen, and this can sometimes cause diagnostic challenges." (PMID 41299396, 2025). "At present, 5 missense mutations in the LMX1B homeodomain that can cause isolated nephropathy have been reported in the relevant literature." (PMID 38457557, 2024). "In conclusion, our report strongly suggests that the pathogenic etiology of this hereditary kidney disease family is most likely attributed to the LMX1B (c.737G > T p.R246L) mutation." (PMID 38457557, 2024). "Upon reviewing the relevant literature, it was found that kidney disease caused by LMX1B gene mutation exists only in NPS with extrarenal manifestations." (PMID 38457557, 2024). "The affected mother was shown to have proteinuria as a result of the progression of kidney disease, with which p.Ser242del can be associated, considering its location within the variant hotspot in the LMX1B homeodomain." (PMID 38424113, 2024). "Advances in genetic testing have enabled the identification of hereditary kidney diseases, including those caused by LMX1B mutations." (PMID 38457557, 2024). "Sanger sequencing confirmed that LMX1B (c.737G > A, p.R246Q) is the pathogenic gene for their kidney disease." (PMID 38457557, 2024). "Here we describe a Chinese family with autosomal dominant nephropathy found to have a novel homeodomain mutation providing further insight into LMX1B-associated kidney disease." (PMID 38457557, 2024). "As demonstrated in the LMX1B mutations causing kidney disease, diseases can arise if transcriptional regulators of slit diaphragm proteins are mutated." (PMID 32708597, 2020). "Two groups have reported the detection of novel missense mutations affecting R246 in the homeodomain of LMX1B in patients with isolated renal disease." (PMID 24809698, 2014). "Indeed, two further case reports recently showed that LMX1B-associated nephropathy can present with Alport syndrome-like phenotype and GBM abnormalities mimicking Alport syndrome." (PMID 41299396, 2025). "It is very important to investigate the mechanisms by which LMX1B mutations lead to nephropathy." (PMID 40868160, 2025). "The precise mechanism by which LMX1B mutations lead to kidney disease is not fully understood." (PMID 40868160, 2025). "The hypothesis put forth suggests that the nephropathy observed in this family is likely attributed to a mutation in the LMX1B gene." (PMID 38457557, 2024). "Therefore, our case is clearly distinguishable from previously reported cases of isolated nephropathy caused by LMX1B mutations." (PMID 28335748, 2017). "Based on these series of experiments, we proposed that the constellation of different glomerular changes in a family with hereditary kidney disease may be a pointer to a diagnosis of kidney specific LMX1B mutation." (PMID 28059119, 2017). "However LMX1B mutations are causative in the syndromic disease nail–patella syndrome characterized by hypoplastic nails and patella, skeletal deformities and varying degrees of nephropathy." (PMID 32708597, 2020). "Combining inheritance pattern, clinical features of kidney disease, and WES analysis, we speculate that a novel mutation in the LMX1B homologous domain of R246L may be the causative gene for hereditary kidney disease in this family." (PMID 38457557, 2024). "Eight heterozygous variants were identified in nephropathy-associated genes (CLCN2, C5orf42, GSN, LMX1B, CEP164, PKD1, ITGB4, and KANK2), but each could be discounted having been inherited from an unaffected parent." (PMID 37148394, 2023).
Nephropathy (continued). "Although comparisons of phenotypes with genotypes have not revealed any relationship between disease severity and the type or location of mutations, specific missense mutations in LMX1B have recently been identified in cases of nephropathy without extrarenal manifestations." (PMID 28335748, 2017). "Similarly, LMX1B mutations cause organ-specific kidney disease without extrarenal involvement." (PMID 33462143, 2021). "However, after detailed physical examination of members of this family, no abnormal manifestations suggestive of NPS were found, and no isolated kidney disease due to LMX1B gene were reported." (PMID 38457557, 2024). "Thus, as with the study by Knoers and colleagues, although there was evidence for familial aggregation of nephropathy, we found no convincing evidence for a specific “nephropathy locus” in LMX1B." (PMID 18535845, 2009).
open-angle glaucoma (9 papers, 2007 to 2025). Chronic outflow obstruction of the eye's drainage canals that can lead to increased internal eye pressure and optic nerve damage. "Rare Mendelian variants in LMX1B can produce early-onset ocular hypertension and open-angle glaucoma (OAG)." (PMID 40272416, 2025).
Parkinson disease (7 papers, 2015 to 2026). A progressive degenerative disorder of the central nervous system characterized by loss of dopamine producing neurons in the substantia nigra and the presence of Lewy bodies in the substantia nigra and locus coeruleus. "Certain transcription factors, e.g., Ascl1 and Lmx1b, seem to be required for specification of many brainstem regions that are susceptible to degeneration in early Parkinson’s disease." (PMID 28685157, 2017). "Interestingly, Lmx1b has also been shown to have a regulatory role in the autophagic lysosomal degradation pathway and intracellular transport functions, where its dysfunction is associated with Parkinson’s disease pathogenesis." (PMID 38168192, 2023). "Relevantly, homozygous conditional knockout of both Lmx1b and Lmx1a as well as siRNA knockdown of Lmx1b alone impact mitochondrial functions in neurons and may contribute to Parkinson’s disease." (PMID 39829808, 2025). "Some have been associated with neurodevelopmental disorders: schizophrenia (DIXDC1, ARVCF, MAGI2, ZIC2), ADHD (attention deficit/hyperactivity disorder) (TCERG1L), movement disorders (NOL3, TP53INP2), Huntington’s disease (H2AFY2, AGPAT1), Parkinson’s disease (LMX1B), and autism (PLXNA4, WNT2)." (PMID 25748564, 2015). "The altered dopaminergic system is one of the pathological elements in RLS as well, and the implication of LMX1B in RLS suggests an overlap between RLS and Parkinson’s disease in terms of their pathogenesis." (PMID 38168192, 2023). "By using a Dat driven Cre, Lmx1b was removed in postmitotic mdDA neurons, which led to dysregulation of the autophagic-lysosal pathway, abnormal synaptic responses and reduced protein levels of striatal TH and DAT expression, all processes that contribute to a Parkinson’s disease pathology." (PMID 30930745, 2019).
Obesity (6 papers, 2020 to 2025). Accumulation of substantial excess body fat. "To summarize, the AA genotype of LMX1B rs10733682 is a potential obesity and lipid profile risk factor in Han Chinese female children." (PMID 32357537, 2020). "Another LMX1B polymorphism loci rs3829849 was found to be associated with obesity in Central Mexican children." (PMID 32357537, 2020). "In the future, we will confirm the relationship between the LMX1B rs10733682 polymorphism and obesity in boys by increasing the sample size." (PMID 32357537, 2020). "The association of the rs10733682 and rs3829849 polymorphisms in LMX1B loci with obesity has been established by GWAS both in adult and pediatric populations and may be possibly explained by the role of LMX1B in serotonergic and dopaminergic pathways." (PMID 36986146, 2023). "The most attractive findings of this study were that the AA genotype of LMX1B rs10733682 was associated with greater incidence of overweight/obesity, central obesity, and higher body weight, WC, BMI, and WHtR; here showed for the first time in Han Chinese female children." (PMID 32357537, 2020). "The purpose of this study was to reveal the association between the LMX1B rs10733682 polymorphism and obesity, as well as to explore the interaction of the LMX1B rs10733682 polymorphism with macronutrients intake, dietary patterns and physical activity levels on obesity risk of Chinese children." (PMID 32357537, 2020). "The nearest gene to rs10733682, LMX1B, is a homeobox transcription factor with a number of developmental functions, and rs10733682 has been nominally associated with decreased satiety responsiveness and shown interactions with macronutrients and dietary patterns in relation to obesity." (PMID 34205853, 2021). "However, whether there is a significant association between the LMX1B rs10733682 polymorphism and obesity in Chinese children remains to be verified." (PMID 32357537, 2020). "Seven SNPs were also associated with obesity in Central Mexican children (SEC16B rs543874, OLFM4 rs12429545, rs9568856, FTO rs9939609, MC4R rs6567160, GNPDA23 rs1330484, and LMX1B rs3829849)." (PMID 31936053, 2020). "This study is the first to indicate the relationship between a novel SNP of LMX1B rs10733682 and general overweightness, obesity, and central obesity in Han Chinese girls." (PMID 32357537, 2020). "Transcripts for several candidate genes for obesity were absent in the whole brain or absent in specific regions of the brain (Cyp17a1, Gdf15, Gpr151, Lmx1b, Olig3, Sbk1, Sim1, Skor1, Tnni3k)." (PMID 39920851, 2025).
autism (4 papers, 2011 to 2017). Persistent deficits in social interaction and communication and interaction as well as a markedly restricted repertoire of activity and interest as well as repetitive patterns of behavior. "An association between autism and common variants in LMX1B has been reported in a small cohort of patients." (PMID 28059119, 2017). "In this study, we examined the association of the transcription factor gene LMX1B with autism in Caucasian population." (PMID 21901133, 2011). "In order to examine the role, if any, of LMX1B with autism pathophysiology, a trio-based SNP association study using 252 family samples from the AGRE was performed." (PMID 21901133, 2011). "In conclusion, we report a possible association of the transcription factor LMX1B with autism pathogenesis." (PMID 21901133, 2011). "This is the first report on the association of LMX1B with autism, though it should be viewed with some caution considering the modest associations we report." (PMID 21901133, 2011). "It is therefore likely that the finding of autism in our patients may represent effects of other variants in LMX1B and other modifier genes." (PMID 28059119, 2017). "Here we performed a trio-based study to examine the association of LMX1B with autism." (PMID 21901133, 2011). "Some of the genes, such as NCAN and EPHA7, have similar functionality as NRXN1 in mediating neuronal cell interactions, while some other genes, such as PCDH19, CNTN3, CTNNA3, LMX1B, are known autism candidate genes." (PMID 23536886, 2013). "LMX1B transcripts was found to be significantly lower in the anterior cingulate gyrus region of autism patients compared with controls (p = 0.049)." (PMID 21901133, 2011). "There was a significant difference in LMX1B expression between the autism and control group in the ACG (p = 0.049)." (PMID 21901133, 2011). "Further, LMX1B mRNA expressions were studied in the postmortem brain tissues of autism subjects and healthy controls samples." (PMID 21901133, 2011). "We also assessed any alterations in the expression LMX1B in the postmortem brain samples of autism patients as compared to healthy controls." (PMID 21901133, 2011). "In view of the importance of LMX1B in the development of 5-HTergic neurons, it would be interesting to study its role in autism." (PMID 21901133, 2011). "Our study suggests a possible role of LMX1B in the pathophysiology of autism." (PMID 21901133, 2011). "The present finding of reduced LMX1B expression in the ACG of autism group, therefore, could have some deleterious effects on the serotonergic system, given the role of LMX1B in the differentiation of 5HT neurons in developing brain, and in the maintenance of 5HT system in adult brain." (PMID 21901133, 2011).